PECAM1 (platelet and endothelial cell adhesion molecule 1)
Diseases named in the same sentence as PECAM1 in open-access papers (continued):
Sharing a sentence is not in itself a finding about the gene and the disease.
leiomyoma (5 papers, 2014 to 2023). A well-circumscribed benign smooth muscle neoplasm characterized by the presence of spindle cells with cigar-shaped nuclei, interlacing fascicles, and a whorled pattern. "Induction of a known fibroid subtype mutation in CRIP1 + /PECAM1- cells and their subsequent development into fibroid-like cells, could advance our understanding of fibroid etiology based on the hypothesis that a dysregulated MyoSPC is the origin of uterine fibroids." (PMID 37400623, 2023). "Inducing common mutations observed in fibroids in CRIP1+/PECAM1- myometrium cells, such as MED12 (exon 2, 131 G > A, G44D) or overexpression of HMGA2, could provide insight into fibroid etiology and models to evaluate alternative therapeutics." (PMID 37400623, 2023). "A total of eight leiomyoma-related DEGs (EGR1, CEBPB, IL6, PECAM1, VWF, TNFRSF1A, CD34 and ACE) were found upregulated in MF versus M only." (PMID 33807176, 2021).
meningitis (5 papers, 2013 to 2025). A disorder characterized by acute inflammation of the meninges of the brain and/or spinal cord. "The predominant cause of meningitis in older infants and children is Streptococcus pneumoniae, which interacts with the endothelial receptors polymeric immunoglobulin receptor (pIgR) and platelet endothelial cell adhesion molecule-1 (PECAM-1 or CD31) to invade the CNS." (PMID 35250814, 2022). "Binding of RrgA to BBB endothelial receptors (PECAM-1 and pIgR) promotes bacterial entry and meningitis development." (PMID 33633703, 2021).
metabolic syndrome (5 papers, 2010 to 2023). A cluster of metabolic risk factors for CARDIOVASCULAR DISEASES and TYPE 2 DIABETES MELLITUS. "Increased PECAM-1 in the serum of patients with SLE may also be modulated by a greater proportion of metabolic syndrome risk factors including increased age, Body Mass Index (BMI) and waist circumference which may increase PECAM-1 levels." (PMID 37516862, 2023). "Patients with the metabolic syndrome have markedly elevated CD31+ (PECAM-1) EMPs." (PMID 20634911, 2010).
pneumococcal meningitis (5 papers, 2017 to 2025). An acute purulent infection of the meninges and subarachnoid space caused by Streptococcus pneumoniae, most prevalent in children and adults over the age of 60. "Adjunct treatment with pIgR and PECAM-1 antibodies to antibiotics may prevent pneumococcal meningitis development and associated brain damage." (PMID 40709930, 2025). "Our data suggest that inhibition of pIgR and PECAM-1 has the potential to prevent pneumococcal meningitis." (PMID 28515075, 2017).
pulmonary hypertension (5 papers, 2019 to 2025). Increased pressure within the pulmonary circulation due to lung or heart disorder. "We previously showed that caspase-dependent cytosolic cleavage of the adherens junction protein PECAM-1 disrupts endothelial shear sensing and adaptation in pulmonary arterial hypertension." (PMID 41227316, 2025).
rheumatoid arthritis (5 papers, 2021 to 2025). A chronic, systemic autoimmune disorder characterized by inflammation in the synovial membranes and articular surfaces. "There is an increased concentration of soluble PECAM-1 in disorders like atherosclerosis, neurodegenerative diseases, rheumatoid arthritis (RA), and metabolic syndrome." (PMID 35268306, 2022).
schwannoma (5 papers, 2013 to 2025). A benign, usually encapsulated slow growing tumor composed of Schwann cells. "MMP9 was strongly colocalized with CD31/PECAM1 + endothelial cells and S100B + schwannoma cells." (PMID 38887507, 2024).
Thrombocytopenia (5 papers, 2021 to 2024). A reduction in the number of circulating thrombocytes. "The recovery of the peripheral platelet count is impaired in PECAM-1−/− mice following experimentally induced thrombocytopenia, which is likely due to a reduced megakaryocyte migration towards endothelium." (PMID 37047732, 2023). "LA, however, dramatically increased PECAM-1/CD31 expression in the alveolar capillaries and pulmonary vascular thrombi (red squares, oval), with the mice developing thrombocytopenia and an elevated activated clotting time." (PMID 35502320, 2022). "In addition to the virus-induced thrombocytopenia in infected HuPBL-NCG mice, we observed disorganization of vascular endothelium in sacrificed mouse lung sections by immunostaining with anti–platelet cell adhesion molecule 1 (PECAM-1; CD31) antibody and H&E staining." (PMID 33974679, 2021).
type 1 diabetes (5 papers, 2014 to 2025). "A study of the role of retinal microvascular PECAM-1 in a type 1 diabetic rat model, as well as in cultured retinal ECs in hyperglycaemic media, reported a significant decrease in PECAM-1 protein levels, which was dependent on MMPs." (PMID 40713559, 2025).
clear cell renal cell carcinoma (4 papers, 2019 to 2023). "For instance, PECAM1 was suggested as an independent prognostic factor in clear cell renal cell carcinoma." (PMID 32196072, 2020). "Therefore, the hub gene CCND1 and PECAM1/CD31 may play key role in the progression of clear cell renal cell carcinoma." (PMID 31850854, 2019).
coagulopathy (4 papers, 2020 to 2021). "Coagulopathy occurs due to the release of tissue factor and platelet endothelial cell adhesion molecule-1 (PECAM-1)." (PMID 34360549, 2021). "Analysis of the targets overlapped such as PTGS1, PTGS2, PIK3CG, and PECAM1 in the pathological processes of hemorheological abnormality and coagulopathy implied that inflammation and immunity were also important for QS-BSS which need further study." (PMID 32190085, 2020). "The study also clarified the changes in plasma concentrations of tissue factor (TF) and platelet endothelial cell adhesion molecule-1 (PECAM-1), and suggested that these have important significance in the etiology and pathogenesis of CAR-T related coagulopathy." (PMID 34359816, 2021).
dementia (4 papers, 2021 to 2023). Loss of intellectual abilities interfering with an individual's social and occupational functions. "Consistent with our findings, XIN1, PECAM1, CD40, and JAMA were also reported to be differentially expressed in the plasma of subjects with dementia compared with MCI." (PMID 37175824, 2023). "Complementarily to these data, we have found differential patterns of astrocytes implication in dementia using additional markers such as AQP4, GS1, GLAST1, and for ECs such as Lectin UEA, vimentin, PECAM1 and CLDN5." (PMID 34025357, 2021). "Phenotypically, NK cells from MS donors displayed a more migratory profile than those from control and dementia cases: higher expression of CD49d (integrin alpha-4), CD54 (ICAM1 or intercellular adhesion molecule 1), and CD31 (PECAM1 or platelet endothelial cell adhesion molecule)." (PMID 35536009, 2022).
endotoxemia (4 papers, 2018 to 2023). "In addition, during LPS-induced endotoxemia, blood vessels of PECAM-1-deficient mice exhibited increased BBB permeability." (PMID 36992502, 2023). "The results showed that RMECs extracted from endotoxemia-treated rats of all groups exhibited decreased mRNA expression of the endothelial markers VE-Cadherin, PECAM-1, von Willebrand Factor (vWF), and collagen type IV (Col IV) compared to saline-treated rats." (PMID 36978907, 2023). "We also measured PECAM-1, an adhesion protein expressed in endothelial cells that mediates leukocyte migration between endothelial cells and, like sICAM-1, is indicated in endotoxemia." (PMID 35135577, 2022). "Endotoxemia-induced endothelial fibrosis is characterized by a massive change in the endothelial gene-expression profile, which downregulates endothelial markers, including vascular endothelial cadherin (VE-cadherin) and platelet endothelial cell adhesion molecule 1 (PECAM-1)." (PMID 36978907, 2023).
esophageal cancer (4 papers, 2015 to 2021). A primary or metastatic malignant neoplasm involving the esophagus. "Of the angiogenic factors VEGF, Angiopoietin-2, PECAM-1, Follistatin, Leptin, G-CSF, HGF, PDGF-BB and IL-8, two angiogenic factors (HGF and Follistatin) are associated with esophageal cancer patients’ prognosis in posttherapeutic tumor tissue." (PMID 25885021, 2015).
Insulin resistance (4 papers, 2012 to 2019). Increased resistance towards insulin, that is, diminished effectiveness of insulin in reducing blood glucose levels. "Early phase of NAFLD, characterized by significant liver steatosis and prominent insulin resistance, was related with LSEC pro-inflammatory phenotype as evidenced by elevated ICAM-1, E-selectin and PECAM-1 expression." (PMID 30809151, 2019). "We investigated the expression levels of PECAM1 and VEGF-A in islets of two animal models for insulin resistance, HFHSD fed mice and db/db mice." (PMID 22384192, 2012).
Peritoneal Fibrosis (4 papers, 2019 to 2024). Disorder characterized by a wide range of structural changes in PERITONEUM, resulting from fibrogenic or inflammatory processes. "In this setting, downregulation of PECAM1 has been reported to be implicated in the reduced angiogenesis and inflammation in peritoneal fibrosis." (PMID 33425898, 2020).
pulpitis (4 papers, 2020 to 2025). Inflammation of the dental pulp. "In this paper, a Limma R Package analysis based on a Gene Expression Omnibus (GEO) pulpitis dataset GSE16134 suggested a possible interaction between PECAM1 and chemokine receptor 4 (CXCR4)." (PMID 33425898, 2020). "CXC-chemokine receptor 4 (CXCR4) combined with recombinant platelet/endothelial cell adhesion molecule (PECAM1) could regulate inflammatory cell infiltration by activating the Nuclear Factor-kappa B (NF-κB) signaling pathway in pulpitis." (PMID 37238161, 2023). "Taken together, by inducing pulpitis models in animals and HDPCs, this study was performed to evaluate the potential functions of PECAM1 and CXCR4 in pulpitis development and the possible involvement of the NF-κB signaling pathway, and to explore the potential regulatory network as well." (PMID 33425898, 2020). "Collectively, it can be concluded that MEF2C promotes transcription and interaction between PECAM1 and CXCR4, therefore promoting inflammatory responses in pulpitis samples." (PMID 33425898, 2020). "Subsequently, we further examined the expression of and correlation between MEF2C and PECAM1 and CXCR4 in the dental tissues of rats in the Sham and Pulpitis groups." (PMID 33425898, 2020). "The high-expression profiles of PECAM1 and CXCR4 were validated in our rat models with pulpitis and in LPS-induced HDPFs." (PMID 33425898, 2020). "A transcription factor myocyte-enhancer factor 2 (MEF2C) was predicted and validated as a positive regulator of either PECAM1 or CXCR4, which activated the NF-κB signaling pathway and promoted pulpitis progression." (PMID 33425898, 2020). "These aroused our attention to probe the interaction of PECAM1 and CXCR4 in pulpitis progression, and the potential molecules involved." (PMID 33425898, 2020). "Importantly, PECAM1 and CXCR4 were analyzed to be highly expressed and highly interacted in pulpitis, while the B-cell signaling pathways were positively correlated with PECAM1 expression." (PMID 33425898, 2020).
sarcoidosis (4 papers, 2015 to 2025). Sarcoidosis is a multisystemic disorder of unknown cause characterized by the formation of immune granulomas in involved organs. "To the best of our knowledge we were the first to demonstrate the serum concentrations of Ang-2, PECAM-1 and follistatin in IPF and sarcoidosis." (PMID 26438257, 2015). "In the sarcoid patients concentrations of serum Ang-2, follistatin, GM-CSF, IL-8, PDGF-BB, PECAM-1 and VEGF were similar to the values noticed in the control group." (PMID 26438257, 2015). "In the sarcoidosis group we found statistically significant relationships between concentrations of Ang-2 and IL-8 (r = 0.62, P < 0.0001), follistatin and PECAM-1 (r = 0.76, p < 0.0001) as well as PDGF-BB and PECAM-1 (r = 0.82, p < 0.0001)." (PMID 26438257, 2015). "In our study elevated serum concentrations of IL-8, GM-CSF, follistatin, PDGF-BB and PECAM-1 in the IPF patients, but not in the sarcoidosis patients even in active progressive disease have been observed." (PMID 26438257, 2015).
systemic sclerosis (4 papers, 2017 to 2023). A chronic disorder, possibly autoimmune, marked by excessive production of collagen which results in hardening and thickening of body tissues. "What is more, evidence from a study of patients with systemic sclerosis and PAH proved that a regimen of bosentan for 12 months could normalize the expression of ICAM-1, VCAM-1, P-selectin, and platelet/endothelial cell adhesion molecule (PECAM-1) and restore T-cell function." (PMID 36901752, 2023).
acute lymphoblastic leukemia (3 papers, 2013 to 2020). Leukemia with an acute onset, characterized by the presence of lymphoblasts in the bone marrow and the peripheral blood. "Expression of VE-cadherin and PECAM-1 enhanced the adhesion of acute lymphoblastic leukemia to brain-derived microvasculature ECs." (PMID 28596914, 2017).
erectile dysfunction (3 papers, 2023 to 2024). Persistent or recurrent inability to achieve or to maintain an erection during sexual activity. "Consistent with this, immunofluorescence staining for PECAM-1, NG2, and NF in CC tissue revealed that shCon MCP-EVs significantly improved endothelial cell, pericyte, and nerve contents in CNI-induced ED mice, thereby ameliorating erectile dysfunction." (PMID 37324943, 2023).
glomerulonephritis (3 papers, 2016 to 2024). A renal disorder characterized by damage in the glomeruli. "PECAM-1 deficiency also causes hyperactivation of B cells to BCR cross-linking, with PECAM-1-deficient mice exhibiting reduced B2 cell numbers in the periphery and increased peritoneal B1 cells, as well autoantibody production, culminating in glomerulonephritis – all features shared by Lyn-/- mice." (PMID 39007135, 2024).
liver cirrhosis (3 papers, 2021). "Our results showed that the expression of cell adhesion molecules, such as CDH1, PECAM1, SELL and CAV1, which are canonical molecules in cell adhesion, was evidently changed in liver cirrhosis." (PMID 34434654, 2021).
metastatic melanoma (3 papers, 2013 to 2022). A melanoma that has spread from its primary site to another anatomic site. "In line with this, the bioinformatic analysis of the TCGA database revealed that the high expression of the genes coding IL6, IL10, IL12, ICAM-1, ICAM-3, PECAM-1, and CD40L in tissues of patients with metastatic melanoma correlates with the better survival prognosis." (PMID 35327461, 2022).
Miscarriage (3 papers, 2021 to 2022). A pregnancy that ends at a stage in which the fetus is incapable of surviving on its own, defined as the spontaneous loss of a fetus before the 22th week of pregnancy. "Our results demonstrated that the coexistence of the polymorphic alleles (PECAM-1-373G and P-Selectin-37674C) of the two studied polymorphisms is associated with statistically significantly increased risk of spontaneous miscarriages." (PMID 35273840, 2022). "It has been suggested that genetic alterations of platelet membrane factors, including PECAM-1 and P-Selectin, are synergistically involved in the pathogenesis of miscarriages and implantation failure." (PMID 35273840, 2022).
papilloma (3 papers, 2015 to 2021). A benign epithelial neoplasm that projects above the surrounding epithelial surface and consists of villous or arborescent outgrowths of fibrovascular stroma. "A number of genes related to cancer stem cells were validated by qRT-PCR, including Cxcl12/Sdf-1, Pdgfra, Lgr5, Lrg1, Pecam1/CD31, H19 and Src2, which were all significantly upregulated in Nanog-papillomas and Nanog-SCCs relative to control papillomas." (PMID 25988972, 2015).
parasite infection (3 papers, 2017 to 2024). "Expression of genes involved in endothelial activation such as PECAM1, and angiogenesis such as VEGF, angiopoietin 1 and 2 are commonly involved in the pathogenesis of parasitic infections." (PMID 29190292, 2017).
peritonitis (3 papers, 2018 to 2024). Inflammation of the peritoneum (tissue that lines the abdominal wall and covers most of the organs in the abdomen). "We used an acute peritonitis model induced by intraperitoneal (i.p.)injection of IL-1β and quantified neutrophil migration within the extravascular space in WT and Pecam1-/- mice by flow cytometry." (PMID 37549051, 2023). "However, extravascular (i.p.)injection of RGD peptides rescued the defective neutrophil accumulation in Pecam1-/- mice upon IL-1β-induced peritonitis." (PMID 37549051, 2023).
pneumonia (3 papers, 2019 to 2023). An acute, acute and chronic, or chronic inflammation focally or diffusely affecting the lung parenchyma, caused by an infection in one or both of the lungs (by bacteria, viruses, fungi, or mycoplasma.). "One of these eight DEPs was platelet endothelial cell adhesion molecule 1 (PECAM‐1), which was found for the first time to be down‐regulated in patients with KD at protein level compared to normal control and pneumonia (two patients) in our study." (PMID 30761252, 2019). "Moreover, the expression of eight DEPs (PECAM1, PGLYRP1, AHCY, BHMT, EML3, ICOSLG, IGHV3‐23 and RTN4RL2) in normal and pneumonia groups (two patients) was quite different from that in the KD group." (PMID 30761252, 2019). "Moreover, the expression of eight of these 30 DEPs (PECAM1, PGLYRP1, AHCY, BHMT, EML3, ICOSLG, IGHV3‐23 and RTN4RL2) clustered normal and pneumonia samples into one group and clustered KD samples into another group, which heightens the importance of these eight DEPs in KD." (PMID 30761252, 2019).
acute respiratory distress syndrome (2 papers, 2021 to 2022). Progressive and life-threatening pulmonary distress in the absence of an underlying pulmonary condition, usually following major trauma or surgery. "PECAM1, an endothelial cell adhesion molecule, played a potentially protective role in lung injury and acute respiratory distress syndrome." (PMID 36387401, 2022). "PECAM1 was reported to be involved in lung repair and regeneration in acute respiratory distress syndrome whereas COL1A1 is correlated with hypoxia markers in NSCLC." (PMID 33511215, 2021).
acute respiratory failure (2 papers, 2022 to 2023). Life-threatening respiratory failure that develops rapidly. "We tested the association of endotheliopathy—indicated by Syndecan-1, sTM, and PECAM-1 levels in plasma—with patient outcomes and disease severity in acute respiratory failure." (PMID 35094711, 2022). "Our findings suggest PECAM-1 as a promising marker for clinical outcomes in acute respiratory failure." (PMID 35094711, 2022). "To find out, we assessed the association of endotheliopathy, as reflected by plasma levels of Syndecan-1, sTM, and PECAM-1, with clinical outcomes and disease severity in acute respiratory failure requiring MV in the ICU." (PMID 35094711, 2022).
alcoholism (2 papers, 2017 to 2018). "The most important reason for pursuing PECAM-1 in alcoholism is that PECAM-1 has been shown to mediate enhanced transendothelial migration of monocytes in response to oxidative stress." (PMID 29035306, 2017). "Although, the mechanisms through which PECAM-1 regulates these opposing functions is not fully understood, it is clear that PECAM-1 plays an important role in maintaining BBB integrity and may contribute to pathological inflammatory phenotype seen in alcoholism." (PMID 29487525, 2018).
autism (2 papers, 2013 to 2020). Persistent deficits in social interaction and communication and interaction as well as a markedly restricted repertoire of activity and interest as well as repetitive patterns of behavior. "It is, therefore, of interest to examine the correlation between serum levels of PECAM-1 and interleukins in very young children with and without autism to clarify how these adhesion molecules in serum may reflect their central function associated with clinical aspects of ASD." (PMID 23773279, 2013).